SLC35D1 (solute carrier family 35 member D1)
Description:
Antiporter that transports nucleotide sugars across the endoplasmic reticulum (ER) membrane in exchange for either their cognate nucleoside monophosphate or another nucleotide sugar. Transports various UDP-sugars including UDP-N-acetyl-alpha-D-glucosamine (UDP-GlcNAc), UDP-N-acetyl-alpha-D-galactosamine (UDP-GalNAc) and UDP-alpha-D-glucuronate (UDP-GlcA), which are used by ER glucosyltransferases as sugar donors for the synthesis of sugar chains of glycoproteins, glycolipids and oligosaccharides. May couple UDP-GlcNAc or UDP-GalNAc efflux to UDP-GlcA influx into the ER lumen that in turn stimulates glucuronidation and subsequent excretion of endobiotics and xenobiotics. Plays a role in chondroitin sulfate biosynthesis, which is important for formation of cartilage extracellular matrix and normal skeletal development (By similarity).
Synonyms: UGTrel7; KIAA0260; SHNKND
Tractability: Antibody: UniProt predicts a signal peptide or a membrane-spanning region. PROTAC: ubiquitination databases record sites on it; its protein half-life has been measured.
Gene: Protein-coding gene on chromosome 1 (66,999,350 to 67,054,159, reverse strand). Ensembl gene ENSG00000116704.
Subcellular location: Endoplasmic reticulum membrane
Pathways (Reactome):
Disease: Defective SLC35D1 causes SCHBCKD
Metabolism: Formation of the active cofactor, UDP-glucuronate
Transport of small molecules: Transport of nucleotide sugars
Gene Ontology:
Molecular function: antiporter activity; UDP-glucuronate transmembrane transporter activity; UDP-N-acetylgalactosamine transmembrane transporter activity; UDP-N-acetylglucosamine transmembrane transporter activity; pyrimidine nucleotide-sugar transmembrane transporter activity
Biological process: pyrimidine nucleotide-sugar transmembrane transport; UDP-glucuronate transmembrane transport; UDP-N-acetylgalactosamine transmembrane transport; UDP-N-acetylglucosamine transmembrane transport
Cellular component: endoplasmic reticulum membrane; endoplasmic reticulum
Genetic constraint (gnomAD): Loss-of-function variants: 23 observed, 33.23 expected, observed/expected ratio (o/e) 0.69, 90% interval 0.5 to 0.98. The upper end of that interval is the gene's LOEUF score, 0.98, which puts it in group 4 of 6, group 1 being the genes least tolerant of losing a copy. Missense variants: 328 observed, 348.81 expected, observed/expected ratio (o/e) 0.94, 90% interval 0.86 to 1.03. Synonymous variants: 161 observed, 141.47 expected, observed/expected ratio (o/e) 1.14, 90% interval 1 to 1.3.
Gene-disease validity (ClinGen):
ClinGen rates the evidence that SLC35D1 causes each of these diseases.
schneckenbecken dysplasia (autosomal recessive): Definitive. Schneckenbecken dysplasia (or chondrodysplasia with snail-like pelvis) is a prenatally lethal spondylodysplastic dysplasia.
Homologues: Orthologues: chimpanzee SLC35D1 (100% identical), dog SLC35D1 (98% identical), rat Slc35d1 (97% identical), macaque SLC35D1 (91% identical), pig SLC35D1 (90% identical), mouse Slc35d1 (84% identical), tropical clawed frog SLC35D1 (83% identical), rabbit SLC35D1 (82% identical), zebrafish slc35d1a (75% identical), guinea pig SLC35D1 (74% identical), zebrafish slc35d1b (67% identical). Paralogues in human: SLC35D2 (50% identical), SLC35D3 (21% identical), SLC35C1 (17% identical), SLC35E2B (16% identical), SLC35E3 (16% identical), SLC35E4 (16% identical), SLC35D4 (15% identical), SLC35H1 (13% identical), SLC35E1 (13% identical).
Diseases named in the same sentence as SLC35D1 in open-access papers:
SLC35D1 is named in the same sentence as 4 diseases in open-access papers, as found by Europe PMC text mining. Sharing a sentence is not in itself a finding about the gene and the disease. The quoted sentences say what the papers report.
schneckenbecken dysplasia (3 papers, 2015 to 2020). "Homozygous and compound heterozygous loss-of-function SLC35D1 mutations have been reported in patients with Schneckenbecken dysplasia." (PMID 32113484, 2020). "Two loci have been implicated in Schneckenbecken dysplasia, SLC35D1, which encodes a nucleotide sugar transporter (NST), and INPPL1 encoding a inositol polyphosphate phosphatase-like type protein." (PMID 31423530, 2019). "Parental exome sequencing identified a novel variant of the SLC35D1 gene, suggesting a diagnosis of Schneckenbecken dysplasia." (PMID 31423530, 2019). "Mutations in the human ortholog of the most animally enriched novel gene, Slc35d1, are causative for Schneckenbecken dysplasia, and we show that a similar phenotype is produced by depletion of the orthologous protein in Xenopus embryos." (PMID 26100918, 2015).
dysplasia (1 paper, 2019). A usually neoplastic transformation of the cell, associated with altered architectural tissue patterns. "As a control, we also generated and tested the previously characterised missense mutation SLC35D1 c.193A > C p.(Thr65Pro) that results in Schneckenbecken dysplasia." (PMID 31423530, 2019). "The reduced transport activity observed for p.(Pro133Leu) was contrasted with in vitro activity for SLC35D1 p.(Thr65Pro), the loss-of-function mutation was associated with Schneckenbecken dysplasia." (PMID 31423530, 2019).
skeletal dysplasia (6 papers, 2012 to 2025). Any Mendelian diseases that affects growth and development of the skeleton. "The Slc35d1‐deficient mouse showed a lethal form of skeletal dysplasia and human SLC35D1 gene pathogenic variants have been described to cause autosomal recessive Schneckenbecken dysplasia [S42]." (PMID 40468979, 2025). "The Slc35d1-deficient mouse showed a lethal form of skeletal dysplasia associated with severe shortening of limbs, abnormal facial structures, a decreased proliferating zone with round chondrocytes, scarce matrices, and reduced CS but not HS in long bones." (PMID 34901009, 2021). "In humans, autosomal recessive mutations in SLC35D1 have been described in a rare lethal skeletal dysplasia (OMIM 269250)." (PMID 32033218, 2020). "SLC35D1 is critical for chondroitin sulphate synthesis and mutations cause Schneckenbecken skeletal dysplasia." (PMID 22876197, 2012). "Furthermore, schneckenbecken dysplasia characterized by perinatally lethal skeletal dysplasia is caused by mutations in SLC35D1." (PMID 34901009, 2021). "In some of them (ALG12-CDG, ALG3-CDG, ALG9-CDG, PGM3-CDG, SLC35D1-CDG), a severe prenatal-onset skeletal dysplasia was observed and associated with an early death." (PMID 34441372, 2021). "Some types of CDG, including ALG3-CDG, ALG6-CDG, ALG9-CDG, ALG12-CDG, PGM3-CDG, CSGALNACT1-CDG, SLC35D1-CDG, and TMEM-165, were reported with well-defined skeletal dysplasia." (PMID 34540767, 2021). "Contrary to PMM2-CDG, skeletal dysplasia was well characterized in other CDGs, including ALG12-CDG, ALG3-CDG, ALG9-CDG, ALG6-CDG, PGM3-CDG, CSGALNACT1-CDG, SLC35D1-CDG and TMEM165-CDG." (PMID 34441372, 2021). "There is a group of CDGs, including ALG12-CDG, ALG3-CDG, ALG9-CDG, ALG6-CDG, PGM3-CDG, CSGALNACT1-CDG, SLC35D1-CDG, and TMEM-165 with well-defined skeletal dysplasia." (PMID 34441372, 2021). "Contrary to PMM2-CDG, all remaining CDG, including ALG12-CDG, ALG3-CDG, ALG9-CDG, ALG6-CDG, PGM3-CDG, CSGALNACT1-CDG, SLC35D1-CDG and TMEM-165, are characterized by well-defined skeletal dysplasia." (PMID 34441372, 2021).
cancer (1 paper, 2020). A tumor composed of atypical neoplastic, often pleomorphic cells that invade other tissues. "Knockout of these genes, such as SLC35D1 and UGCG, would not directly affect the cancer cell growth, but could alter the micro-environment of cancer cells." (PMID 32085724, 2020).